KRT6B (keratin 6B)
Description:
Structural component of intermediate filaments in epithelial keratinocytes. Forms heteropolymers with the type I keratins KRT16 and KRT17, assembling keratin intermediate filament networks that contributes to the structural integrity and stress resilience of stratified epithelia and appendages. Induced during epidermal stress and wound repair, where it regulates keratinocyte migration and epithelial regeneration (By similarity). Negatively regulates collective keratinocyte migration by stabilizing non-muscle myosin MYH9 and desmoplakin, thereby altering cell-cell and cell-matrix adhesion and reducing the speed and directionality of epithelial sheet movement during wound repair (By similarity). Required for normal palmoplantar, nail unit and oral mucosa integrity.
Synonyms: CK-6B; K6B; KRTL1; CK6B; PC2; PC4
Tractability: PROTAC: ubiquitination databases record sites on it.
Gene: Protein-coding gene on chromosome 12 (52,446,651 to 52,452,146, reverse strand). Ensembl gene ENSG00000185479.
Subcellular location (Human Protein Atlas): Intermediate filaments
Pathways (Reactome):
Developmental Biology: Formation of the cornified envelope; Keratinization
Gene Ontology:
Molecular function: protein binding; structural constituent of cytoskeleton; structural constituent of skin epidermis
Biological process: ectoderm development; intermediate filament organization; keratinization; negative regulation of cell migration
Cellular component: extracellular exosome; cytosol; keratin filament
Genetic constraint (gnomAD): Loss-of-function variants: 29 observed, 43.51 expected, observed/expected ratio (o/e) 0.67, 90% interval 0.5 to 0.91. The upper end of that interval is the gene's LOEUF score, 0.91, which puts it in group 3 of 6, group 1 being the genes least tolerant of losing a copy. Missense variants: 600 observed, 664.67 expected, observed/expected ratio (o/e) 0.9, 90% interval 0.84 to 0.97. Synonymous variants: 213 observed, 253.74 expected, observed/expected ratio (o/e) 0.84, 90% interval 0.75 to 0.94.
Homologues: Orthologues: chimpanzee KRT6B (99% identical), mouse Krt6a (86% identical), mouse Krt6b (84% identical), rat LOC100365213 (83% identical), rat LOC120093742 (83% identical), rat Krt6c (82% identical), rat LOC102553726 (80% identical), mouse Gm5414 (70% identical), rat AABR07001416.1 (70% identical). Paralogues in human: KRT6C (99% identical), KRT6A (99% identical), KRT5 (79% identical), KRT75 (71% identical), KRT3 (66% identical), KRT76 (65% identical), KRT1 (64% identical), KRT2 (62% identical), KRT79 (61% identical), KRT4 (59% identical), KRT77 (56% identical), KRT73 (55% identical), and 56 more.
Diseases named in the same sentence as KRT6B in open-access papers:
KRT6B is named in the same sentence as 53 diseases in open-access papers, as found by Europe PMC text mining. Sharing a sentence is not in itself a finding about the gene and the disease. The quoted sentences say what the papers report.
breast carcinoma (10 papers, 2015 to 2024). "This is significant as KRT6B is typically expressed at higher levels in basal-like breast cancers, a type of cancer type common among BRCA1 mutation carriers." (PMID 38059556, 2024). "KRT6A and KRT6B are associated with pachyonychia congenita, as well as renal carcinoma and breast cancer progression." (PMID 29069744, 2017). "Overexpression of KRT6B was associated with worse DFS in younger patients with HER2-enriched breast cancer only (p = 0.01, HR 4.1); an inverse relationship was seen in older patients in this group (p = 0.14, HR 0.65)." (PMID 25999348, 2015). "Similar to our results, the in silico breast cancer studies found reduced KRT6B and KRT6C levels in the tumor tissues, compared to the cancer-free samples." (PMID 39000463, 2024). "PCK1, LPL, and SFRP2 play a role in breast cancer’s initial and developmental stages, and KRT6B is exclusively related to the developmental stages." (PMID 38791477, 2024). "There were few differences between BRCA1 and BRCA2 as KRT6B, a breast cancer stem cell marker, is upregulated in LASP cells of BRCA1 mutation carriers compared with others." (PMID 38059556, 2024). "Overexpression of ANGPTL4 was associated with inferior outcome for young women with basal breast tumors; the same held true for the keratins (KRT5, KRT6A, and KRT6B) among young women with HER2-enriched breast cancer." (PMID 25999348, 2015). "Furthermore, the expression of several cytokeratin genes such as KRT5, KRT6B, KRT14, and KRT17 was associated with basal-like breast cancer, a breast cancer subtype that is highly associated with poor treatment outcome." (PMID 35911770, 2022). "However, further research is needed to analyze the mechanism of the genes SHC2, KRT6B, and SFRP2 in breast cancer liver metastasis." (PMID 38791477, 2024). "Some genes associated with cell adhesion were analyzed from this radiation- and estrogen-induced experimental breast cancer model, including E-cadherin gene CDH1, DSC3, GJA1, the Integrin alpha 6 gene ITGA6, the Integrin beta 6 gene ITGB6, the Keratin genes KRT14, KRT16, KRT17, KRT6B, and LAMB3." (PMID 36293530, 2022). "Moreover, the KRT6B and KRT15 were reported as the markers of basal-like breast cancers." (PMID 34795689, 2021).
pachyonychia congenita (10 papers, 2017 to 2025). Pachyonychia congenita (PC) is a rare genodermatosis predominantly featuring painful palmoplantar keratoderma, thickened nails, cysts and whitish oral mucosa. "Pachyonychia congenita (PC, OMIM #167200, #167210, #615726, #615728, and #615735) is a rare autosomal dominant disorder caused by keratin gene mutations in KRT6A, KRT6B, KRT6C, KRT16 or KRT17." (PMID 34724947, 2021). "Pachyonychia congenita (PC) is a rare hereditary condition affecting keratinization, which results from an underlying genetic mutation in one of the five keratin genes: KRT6A, KRT6B, KRT6C, KRT16, or KRT17." (PMID 40686559, 2025). "Mutations in KRT6B and KRT17 are responsible for pachyonychia congenita." (PMID 30061793, 2018).
lung carcinoma (5 papers, 2022 to 2025). "The results obtained from RT-qPCR indicated that the expression of KRT6B was markedly elevated in four lung cancer cell lines, in contrast to the normal BEAS-2B cell line (p < 0.01)." (PMID 40092988, 2025). "Subsequently, KRT6B was knocked down, and CCK8 assays demonstrated that KRT6B significantly enhances the proliferative capacity of lung cancer cells, thereby promoting tumorigenesis in lung cancer." (PMID 40092988, 2025). "The results of the CCK8 assay showed a notable reduction in absorbance for both cell lines when KRT6B was knocked down, in comparison to the control groups, indicating that KRT6B promotes lung cancer cell proliferation (p < 0.01)." (PMID 40092988, 2025). "What’s more, we confirmed the high expression of KRT6B in lung cancer cells through RT-qPCR." (PMID 40092988, 2025). "Although cytokeratin detection could be due to epidermal contamination, cytokeratins have previously been shown to be the most abundant proteins in EBC30, and both KRT6A and KRT6B have been identified as potential biomarkers for lung carcinomas in EBC proteomic analyses." (PMID 37147394, 2023). "Subsequently, we used siRNA-mediated knockdown of KRT6B expression in the A549 and NCI-H358 lung cancer cell lines and conducted CCK8 assays." (PMID 40092988, 2025). "KRT6B and KRT10 were found to be abundant in exhaled breath condensate and to be potential biomarkers for the early diagnosis of lung cancer." (PMID 35512017, 2022). "The studies based on proteomic analysis of exhaled breath condensate in the group of patients with lung cancer, in the healthy volunteers and additionally on primary human gingival epithelial cells, showed that KRT6A and KRT6B proteins were elevated in 58.1% of smokers in both groups." (PMID 39000463, 2024).
melanoma (5 papers, 2019 to 2025). A malignant, usually aggressive tumor composed of atypical, neoplastic melanocytes. "Increased expression of KRT6B, KRT14, and KRT17 was associated with poor survival in melanoma." (PMID 36553569, 2022). "As the expression levels of DSC2, DSC3, DSG1, KRT6B, PKP1, and PKP3 increased, the overall survival time of trunk subtype melanoma patients significantly decreased." (PMID 38660305, 2024). "Our analysis, grounded in WGCNA and PPI networks, identified six genes (DSC2, DSC3, DSG1, KRT6B, PKP1, PKP3) with pivotal roles in melanoma’s oxidative stress response and immune infiltration." (PMID 38660305, 2024). "All genes except the two keratin genes (KRT6B and KRT17) were up-regulated in cutaneous melanoma compared to primary melanoma." (PMID 31199813, 2019). "The results indicate that in trunk subtype melanomas, the protein expression levels of DSC2, DSC3, DSG1, KRT6B, PKP1, and PKP3 are significantly higher than those in adjacent normal samples, suggesting the crucial roles of these central genes in SKCM progression." (PMID 38660305, 2024). "Genes, such as members of the keratin family (KRT17, KRTDAP, KRT6B, KRT14, KRTAP13-2) are expressed more in primary tumor, possibly indicating the differentiated status of less advanced cancers, or this could be a disruption in their normal expression by melanoma processes." (PMID 36553569, 2022).
bladder cancer (4 papers, 2022 to 2025). "Additionally, clinical correlation analysis showed that the elevated level of KRT6B was highly associated with bladder cancer stage, grade, and metastasis status." (PMID 35794606, 2022). "GSEA revealed that KRT6B was involved not only in epithelial–mesenchymal transition-related pathways but also in the immune response in bladder cancer." (PMID 35794606, 2022). "KRT6B, which can be detected in bladder cancer-derived exosomes, plays an important role in the epithelial–mesenchymal transition and immune responses in bladder cancer." (PMID 35794606, 2022). "Survival analysis based on the UALCAN database showed that among the top 10 upregulated and the top 10 downregulated exosomal genes, only the expression of KRT6B had a statistically significant effect on the survival of bladder cancer patients." (PMID 35794606, 2022). "KRT6B, a molecule significantly related to epithelial-mesenchymal transition and immune mechanisms, was detected elevated in bladder cancer-derived exosomes, indicating its crucial role in the invasion and metastasis of bladder cancer process." (PMID 37805491, 2023). "It reveals that KRT6B, associated with epithelial-mesenchymal transition (EMT) and immune response, could serve as a significant prognostic marker and therapeutic target in bladder cancer." (PMID 40395335, 2025). "Interestingly, the high-degree gene KRT6B has been implicated in the regulation of epithelial–mesenchymal transition (EMT) and immune-related pathways, including macrophage differentiation and polarization, as demonstrated in studies of bladder cancer." (PMID 40076979, 2025).
psoriasis (4 papers, 2015 to 2025). An autoimmune condition characterized by red, well-delineated plaques with silvery scales that are usually on the extensor surfaces and scalp. "KRT6B is known to be strongly induced in keratinocytes after hyperproliferative stimuli such as wound healing, psoriasis, and other inflammatory disorders." (PMID 25740152, 2015). "A series of psoriasis-related genes, such as S100A8, S100A9, KRT6A (keratin 6A), KRT6B, KRT6C, KRT16, and MMP9 (metalloproteinase 9), were also down-regulated." (PMID 35273606, 2022). "Further psoriasis and AD share the KRT6A, KRT6B, KRT6C, KRT16, KRT17 as their common DEGs." (PMID 35874668, 2022).
breast tumor (3 papers, 2015 to 2024). "SHC2, LPL, PCK1, and KRT6B were all under-expressed, and only SFRP2 was highly expressed in the breast tumor." (PMID 38791477, 2024).
breast invasive carcinoma (2 papers, 2022 to 2024). "For the five genes (LPL, PCK1, KRT6B, SFRP2, SHC2) that were differentially expressed between the datasets, we analyzed the alterations in metastatic breast cancer and invasive breast cancer genetic profiles." (PMID 38791477, 2024).
hepatoma (2 papers, 2022). "KRT6B was considered as a key mediator of notch signaling in honokiol-induced human hepatoma cell apoptosis." (PMID 36072430, 2022). "The overexpression of KRT6B has been shown to significantly suppress honokiol-induced human hepatoma cell apoptosis via notch signaling." (PMID 35740697, 2022).
pterygium (2 papers, 2022 to 2024). A wedge-shaped fibrovascular lesion arising from the bulbar conjunctiva and extending to the cornea. "The SVM algorithm was also employed to rigorously select hub genes associated with pterygium, revealing five significant genes: KRT10, KRT6B, BTG2, ASPG and NGEF." (PMID 39722894, 2024).
renal carcinoma (2 papers, 2017 to 2019). A carcinoma arising from the epithelium of the renal parenchyma or the renal pelvis. "In addition, we found an elevated expression of KRT6B, a member of the extracellular matrix protein family known to interact with Notch1 and contribute to renal carcinoma progression." (PMID 31092844, 2019).
adenoma (1 paper, 2021). A neoplasm arising from the epithelium. "The KRT6A and KRT6B gene transcripts were significantly elevated in the adenoma (one case) compared to malignant tumors." (PMID 34065672, 2021).
adenosquamous carcinoma (1 paper, 2021). A carcinoma composed of malignant glandular cells and malignant squamous cells. "Since the pathological tumor tissue was adenosquamous carcinoma, we observed several keratins, including KRT1, KRT6B, KRTDAP, and KRT10, in C5." (PMID 34326696, 2021).
alopecia (1 paper, 2021). Hair loss usually from the scalp. "However, given the observed alopecia, it is somewhat surprising that transcripts for hair-follicle-specific keratins (Krt6a, Krt6b, and Krt17) were increased." (PMID 34445339, 2021).
cholesteatoma (1 paper, 2012). A pathologic process characterized by the proliferation of keratinizing squamous epithelium resulting in the accumulation of keratin and cells in the middle ear and/or mastoid. "Cytokeratin 6b (KRT6B) and Cytokeratin 14 immunostainings verified increased expression levels in cholesteatoma at protein level." (PMID 23285167, 2012). "Real-time PCR of PI3, SPRR1B, LCN2 (lipocalin 2), MMP1, MMP9, MMP10, MMP12, SPP1, GJB2, Bcl-xl (BCL2L1), cIAP2 (BIRC3), S100A7A (koebnerisin), S100A9, SERPINB3, CEACAM6, KRT6B and SERPINB4 revealed that the expression levels of these proteins were higher in cholesteatoma than in external canal skin." (PMID 23285167, 2012).
colorectal cancer (1 paper, 2024). A primary or metastatic malignant neoplasm that affects the colon or rectum. "On the contrary, increased KRT6B expression was demonstrated in colorectal cancer, compared to healthy colorectal mucosal tissue, based on the results of bioinformatics analyses." (PMID 39000463, 2024).
dental caries (1 paper, 2018). The decay of a tooth, in which it becomes softened, discolored, and/or porous. "Given that KRT6B harbors three missense SNPs showing significant association with caries experience, we wanted to further quantify the genetic relationship of missense variants in this gene on dental caries." (PMID 29357356, 2018). "Using genetic and intraoral examination data from 573 adults and 449 children, we identified several missense polymorphisms in KRT6A, KRT6B and KRT6C that lead to a higher risk for dental caries." (PMID 29357356, 2018).
head and neck cancer (1 paper, 2024). A primary or metastatic malignant neoplasm affecting the head and neck. "In head and neck cancer tissues, KRT6B gene expression exceeded that of normal tissues." (PMID 38398015, 2024). "When comparing 11 pairs of head and neck cancer tissues with normal tissues, both KRT6A and KRT6B showed a significant increase in tumor tissues." (PMID 38398015, 2024).
head and neck squamous cell carcinoma (1 paper, 2024). A squamous cell carcinoma that arises from any of the following anatomic sites: lip and oral cavity, nasal cavity, paranasal sinuses, pharynx, larynx, and salivary glands. "The aim of this study was to evaluate type II cytokeratins (KRT): KRT6A, KRT6B, and KRT6C protein concentrations in 54 tumor and margin samples of head and neck squamous cell carcinoma (HNSCC)." (PMID 39000463, 2024).
injury (1 paper, 2024). Damage inflicted on the body as the direct or indirect result of an external force, with or without disruption of structural continuity. "Hericium erinaceus mycelia could regulate epidermal differentiation by decreasing the expression of Krt16 and Krt6b, thus alleviating ethanol-induced chronic gastric injury in mice." (PMID 38213743, 2024).
metastatic tumors (1 paper, 2019). "Among them, ITGB1, TWIST1 and KRT6B are consistently up-regulated in metastatic tumors of both MB49 sub-clones." (PMID 31092844, 2019).
oral cancer (1 paper, 2024). "The increased mRNA expression levels of KRT6A and KRT6B in the paired tumor tissues of our oral cancer patients also confirmed this clinical observation." (PMID 38398015, 2024).
ovarian carcinoma (1 paper, 2017). A malignant neoplasm originating from the surface ovarian epithelium. "KRT5 and KRT6 (KRT6A, KRT6B & KRT6C) gene expression was assessed in publically available serous ovarian cancer data sets, ovarian cancer cell lines and primary serous ovarian cancer cells." (PMID 28147318, 2017).
Ovarian tumors (1 paper, 2024). "Ovarian tumors exhibit heterogeneity with distinct cell types expressing stem cell markers cluster of differentiation 133 (CD133), leucine-rich repeat-containing G-protein coupled receptor 5 (LGR5), aldehyde dehydrogenase 1 (ALDH1), and cytokeratin 6B (CK6B)." (PMID 38434767, 2024).
Sjögren’s syndrome (1 paper, 2016). "The upregulation of keratin 6b has also been demonstrated in conjunctival epithelium of patients with Sjögren’s syndrome." (PMID 27023475, 2016).
viral infections (1 paper, 2020). "The MERS-CoV-shared genes KRT6B and TNFAIP3 had a high p-value associated with SARS-CoV-2, whereas genes such as OAS1-3, IRF9, IRF7, STAT1, PML and IFIH1 were highly associated with host responses to viral infections and type I interferon." (PMID 33301474, 2020).